CYP3A5 (cytochrome P450 family 3 subfamily A member 5)
Diseases named in the same sentence as CYP3A5 in open-access papers (continued):
Sharing a sentence is not in itself a finding about the gene and the disease.
kidney transplant (17 papers, 2019 to 2026). A surgical procedure in which one or both kidneys from a donor are implanted into a recipient. "Although pharmacogenetic studies in Latin American populations remain limited, research conducted in Mexican kidney transplant recipients similarly showed that CYP3A5 genotype is strongly associated with tacrolimus pharmacokinetic variability." (PMID 40432883, 2025). "Prevalently, most of the studies suggested that CYP3A5 polymorphism contributes significantly lower the efficiency of tacrolimus dosage and forces patients to take the higher dosage in post-kidney transplant patients in NS." (PMID 39925446, 2025). "One of the principal strengths of this study is its novelty and regional relevance, as it represents one of the first pharmacogenetic evaluations of CYP3A5 polymorphisms in pediatric kidney transplant recipients in Guatemala." (PMID 40432883, 2025). "A meta-analysis on the association between CYP3A5*3 and tacrolimus response in kidney transplant recipients revealed that CYP3A5*1 allele carriers had a higher risk of acute rejection and chronic nephrotoxicity than CYP3A5*3/*3 carriers." (PMID 34357144, 2021). "In the current study, we investigated the influence of CYP3A5 genotype on TAC pharmacokinetics in a cohort of Guatemalan pediatric kidney transplant recipients." (PMID 40432883, 2025). "This study in 45 Guatemalan pediatric kidney transplant recipients identified significant differences in tacrolimus pharmacokinetics according to CYP3A5 genotype." (PMID 40432883, 2025). "Based on these findings, we advocate for the routine implementation of CYP3A5 genotype-guided tacrolimus dosing in pediatric kidney transplant recipients." (PMID 40432883, 2025). "Recently, a GWAS study in 251 Chinese kidney transplant recipients evaluating more than 773,000 SNPs concluded that CYP3A5*3 genotype accounted for an intervariability in TAC levels of >37%." (PMID 39457109, 2024). "In the case of CYP3A5, 25.64% (10/39) of PGx tests led to adjustments in the starting dose of Tacrolimus in eligible kidney transplant patients." (PMID 37927587, 2023). "The aim of this study was to investigate the influence of single nucleotide polymorphisms in genes encoding metabolizing enzymes (CYP3A5) and transporters (ABCC2) on clinical outcomes (acute graft failure and/or acute tubular necrosis (ATN)) in kidney transplant recipients (KTR)." (PMID 38673067, 2024). "Moreover, we studied the potential impacts of CYP3A4 and CYP3A5 genotypes on post-kidney transplant complications such as delayed graft function, rejection, BK infections, viral acute graft pyelonephritis, and suspected calcineurin inhibitor nephrotoxicity." (PMID 38610733, 2024). "Interestingly, a previous study conducted among Jordanian kidney transplant recipients revealed a correlation between genetic variations in both CYP3A4 and CYP3A5 enzymes and tacrolimus blood levels among renal transplant recipients." (PMID 36042898, 2022).
malaria (10 papers, 2013 to 2025). Malaria is a serious and sometimes fatal disease caused by a parasite that commonly infects a certain type of mosquito which feeds on humans. "CYP3A4, CYP3A5 variants impact Lumefantrine response in a cohort of pregnant women with malaria in Tanzania." (PMID 32858798, 2020). "Taken together, these results indicate that CYP2C8, CYP2C9 and CYP3A5 genetic variants potentially influence in CQ/PQ malaria treatment and should be better evaluated further in larger studies to prevent ineffective treatment and adverse effects." (PMID 27767381, 2016). "The present study also reported a trend for a gene over time interaction between lower parasite elimination rates during malaria treatment and CYP3A5 splicing defect alleles (CYP3A5*3 and *6) carriers." (PMID 27767381, 2016). "CYP2C8 along with CYP2B6, CYP3A4, and CYP3A5 metabolize drugs used in artemisinin-based combination therapy for malaria, and alleles such as CYP2C8*2, CYP2C8*3, CYP2B6*6, CYP3A4*1B, and CYP3A5*3 may affect patient response to this treatment." (PMID 36834793, 2023). "Through Mendelian randomization, the authors also demonstrated a causal relationship between CYP3A5 eQTLs and reticulocyte counts, proposing a possible evolutionary advantage—such as malaria resistance—that may explain the prevalence of expression alleles in African populations." (PMID 41009956, 2025). "This study reports an association study between the ABCB1 c.3435C>T, CYP3A4*1B (g.-392A>G), CYP3A5*3 (g.6986A>G) SNPs and artemether + lumefantrine treatment outcome in 103 uncomplicated malaria patients from Angola." (PMID 28934955, 2017). "The major finding includes: (i) CYP3A5 genotype has significant influence on plasma LF concentration and (ii) CYP3A4*1B is associated with malaria treatment outcome." (PMID 28673292, 2017). "For this purpose, functional variant alleles in CYP450 (CYP2B6, CYP3A4, CYP3A5) and ABCB1 genes involved in the metabolism of anti-malarial drugs were assessed in pregnant malaria patients treated with ALu." (PMID 28673292, 2017). "Preliminary finding indicates that pharmacogenetic variation in CYP3A4 and CYP3A5 influences the LF plasma exposure and malaria treatment outcome in pregnant women." (PMID 28673292, 2017). "This may indicate that CYP3A5 plays a minor role compared to CYP3A4 in determining malaria treatment outcome." (PMID 28673292, 2017). "The study also indicates a possible role of CYP2C9 and CYP3A5 in malaria treatment." (PMID 27767381, 2016). "Considerable intra-African population structuring at the CYP3A5 gene suggests that there are likely to be multiple pharmacogenetics profiles for key drugs used across the continent, including many used in the treatment and control of malaria and HIV-1." (PMID 23641907, 2013). "The possible influence of genetic variations in CYP2B6, CYP3A5 and ABCB1 on malaria treatment outcome was evaluated using Cox regression analysis." (PMID 28673292, 2017). "Results therefore show that pharmacogenetic variations in CYP2B6 and CYP3A5 influence plasma disposition of artemether and lumefantrine and likely affect malaria treatment outcome if medication is not adhered to." (PMID 38685044, 2024). "In light of the greater contribution of CYP3A4 to ivermectin metabolism rather than CYP3A5, it seems unlikely that pharmacogenetic differences between malaria endemic regions would be of importance." (PMID 37355605, 2023). "However, there was no significant impact of CYP3A5 genotype on malaria treatment outcome which is similar to previous reports." (PMID 28673292, 2017). "No significant influence of CYP2B6, CYP3A5 and ABCB1 c.4036A>Genotypes on malaria treatment outcome were observed." (PMID 28673292, 2017).
diabetes (8 papers, 2008 to 2025). "Multifactor dimensionality reduction analysis confirmed ABCB1 2677 G>T/A as the major determinant of post-transplant diabetes, which is having strong interaction with CYP3A5*3 polymorphism." (PMID 29621269, 2018). "The gene-gene interactions between ABCB1 and CYP3A5 also influence the risk for post-transplant diabetes." (PMID 29621269, 2018). "The objective of the current study was to explore the role of ABCB1 and CYP3A5 genetic polymorphisms in predicting the bioavailability of tacrolimus and the risk for post-transplant diabetes." (PMID 29621269, 2018). "Furthermore, the presence of variant alleles at ABCB1 2677 and CYP3A5*3 was shown to increase the risk for post-transplant diabetes based on our MDR model, which coincides with the higher bioavailability of tacrolimus in this genotype combination." (PMID 29621269, 2018). "Multifactor dimensionality reduction analysis (MDR) revealed that synergistic interactions between CYP3A5*3 and ABCB1 2677 G>T/A as the determinants of risk for post-transplant diabetes." (PMID 29621269, 2018). "Adjusting for CYP3A4 and CYP3A5 variation, BMI, smoking status, diabetes, CKD, and race did not significantly impact this finding." (PMID 41295213, 2025).
prostate carcinoma (8 papers, 2008 to 2025). A carcinoma that arises from epithelial cells of the prostate gland. "Conversely, the inhibition of CYP3A5 has been shown to suppress prostate cancer growth by increasing the nuclear translocation of the androgen receptor." (PMID 39754188, 2025). "Intratumoral activation of CYP3A5 in prostate cancer is reported to mediate the growth of prostate cancer cells by facilitating nuclear translocation of AR." (PMID 36359206, 2022). "Since CYP3A5 is the major P450 CYP isoform expressed in the prostate tissue, the effects observed in our experiments is primarily due to inhibition of CYP3A5 in the tested prostate cancer cell lines." (PMID 34570813, 2021). "We selected bergamottin for this study to monitor if it can be used as an CYP3A5 inhibitor to reduce AR activation and block prostate cancer growth." (PMID 34570813, 2021). "Understanding the biological mechanisms of how bergamottin regulates AR signaling in prostate cancer patients can help establish its mechanism based role in blocking prostate cancer growth especially in AAs expressing high CYP3A5 to reduce health disparity." (PMID 34570813, 2021). "To test the effect of bergamottin on prostate cancer growth we used two cell lines one of AA origin (MDAPCa2b) expressing wild type CYP3A5 and the other of CA origin (LNCaP) carrying mutant CYP3A5." (PMID 34570813, 2021). "Our recent studies have shown that CYP3A5 inhibition can block androgen receptor (AR) signaling, critical for prostate cancer growth." (PMID 34570813, 2021). "In our previous studies we have shown that CYP3A5 expressed in intratumoral prostate regulates AR expression regulating prostate cancer cell growth." (PMID 34570813, 2021). "In conclusion, this data supports our earlier observation that CYP3A5 plays a major role in AR regulation, thus modulating AR downstream signaling and prostate cancer growth." (PMID 32316460, 2020). "Previously we demonstrated that CYP3A5 facilitates nuclear translocation of androgen receptor in prostate cancer cells." (PMID 32316460, 2020). "c-MYC, also significantly downregulated with CYP3A5 siRNA treatment, is one of the key genes amplified in prostate cancer progression." (PMID 32316460, 2020). "Androgen receptor signaling is crucial for prostate cancer growth and is positively regulated in part by intratumoral CYP3A5." (PMID 32316460, 2020). "Prevalent expression of wild type CYP3A5 (*1/*1) form can promote AR activation in the AA prostate cancer patients as compared to NHWA." (PMID 32316460, 2020). "As African American (AA) men often carry the wild type CYP3A5 and express high levels of CYP3A5 protein, we blocked the wild type CYP3A5 in AA origin prostate cancer cells and tested its effect on androgen receptor signaling." (PMID 32316460, 2020). "We have previously shown that CYP3A5 is expressed in androgen receptor positive prostate cancer cell lines (LNCaP, C4-2 and 22RV1) and promotes activation of AR and prostate cancer growth." (PMID 32316460, 2020). "Healthy prostate epithelia are shown to express high basal levels of CYP3A5, but CYP3A5 expression in prostate cancer tissues is less well-characterized." (PMID 32316460, 2020). "We find that two out of five genes (CYP3A5 and LPIN1) with a gene-wise q value equal to zero have previously been associated with prostate cancer, and indeed both genes seem to correspond to a switch in the dominant isoforms." (PMID 28784146, 2017). "In addition, by promoting androgen receptor (AR) nuclear translocation, CYP3A5 governs the proliferation of prostate cancer cells." (PMID 36983670, 2023). "CYP3A5 is the main extrahepatic P450 form expressed in both normal prostate and in prostate cancer." (PMID 34570813, 2021). "Our data suggests that bergamottin may suppress prostate cancer growth, especially in African American (AA) patients carrying wild type CYP3A5 often presenting aggressive disease." (PMID 34570813, 2021).
prostate carcinoma (continued). "Since CYP3A5 is the major extrahepatic CYP3A isoform expressed in prostate and regulates AR activation, the presence of these SNPs in CYP3A5 may alter prostate cancer occurrence growth and treatment resistance in a race-dependent manner." (PMID 32316460, 2020). "Hence bergamottin, a CYP3A5 inhibitor, can play an important role in treating prostate cancer." (PMID 34570813, 2021). "Androgen receptor-regulated signaling pathways play a key role in the progression of the prostate cancer in which androgen-metabolizing enzymes CYP3A4, CYP3A5, and CYP3A43 are expressed." (PMID 36359206, 2022). "Men with prostate cancer undergoing ADT are often elderly and have comorbidities requiring concomitant prescription medications, many of which are CYP3A5 inducers or inhibitors." (PMID 32316460, 2020). "The other major difference between the previously reported results in the DU145 AR negative prostate cancer cell line suggests bergamottin’s action is CYP3A5—AR signaling dependent." (PMID 34570813, 2021).
ovarian carcinoma (7 papers, 2015 to 2024). A malignant neoplasm originating from the surface ovarian epithelium. "Considering the apparent scarcity of investigations and their limited sample sizes, studies on the polymorphisms of the CYP2D6, CYP2E1, and CYP3A5 genes demonstrate a lack of genotype associations with ovarian cancer susceptibility." (PMID 38001897, 2023). "Nonexpressers of CYP3A5 (carriers of CYP3A5*3) in Chinese epithelial ovarian cancer patients were at an increased risk of developing toxicity induced by the combination of paclitaxel/carboplatin." (PMID 32581794, 2020). "A later study investigated the presence of taxane-metabolizing enzymes in ovarian cancer and found that CYP3A4 is expressed at very low levels in ovarian cancer, while CYP3A5 and CYP2C8 were expressed in the majority of ovarian tumors, regardless of histologic type, stage, or grade." (PMID 31309254, 2019). "Research indicates that CYP2C8 and CYP3A5 are prominently expressed in the majority of ovarian tumors, showing higher IHC staining intensity of CYP3A5 and other CYP enzymes in primary ovarian cancer tissues." (PMID 38764576, 2024). "In contrast, high mRNA expression of CYP2A6, CYP2C9, CYP2J2, CYP3A4, CYP3A5, CYP3A7, and CYP3A43 connoted a good prognosis for ovarian cancer patients." (PMID 38001897, 2023). "Further, a series of genes, such as cyclin E1 (CCNE1), cyclin B2 (CCNB2), cytochrome P450 family 3 subfamily A member 5 (CYP3A5), and vascular endothelial growth factor A (VEGFA), have been predicted as target genes for diagnosing ovarian cancer." (PMID 29482638, 2018).
asthma (5 papers, 2013 to 2025). "The genomic DNA extracted from saliva was used in a study, which hypothesized that associations between asthma outcomes and CYP3A5 polymorphisms may result from the altered metabolism of beclomethasone dipropionate." (PMID 40358859, 2025). "This study tested the hypothesis that single-nucleotide polymorphisms (SNPs) in Cytochrome P450 3A5 (CYP3A5) would affect asthma outcomes." (PMID 38928254, 2024). "Identifying CYP3A5 variations may help individualize the dosing of the existing asthma control medications to improve asthma control." (PMID 40358859, 2025). "Detection of CYP3A5*3/3, CYPA35*1/*3, and CYP3A5*1/*1 could impact inhaled steroid treatment strategies for asthma in the future." (PMID 38928254, 2024). "Prior work demonstrated that the five most commonly prescribed glucocorticoids used in the treatment of asthma are metabolized by CYP3A enzymes, specifically CYP3A4, CYP3A5, and CYP3A710,11." (PMID 24555085, 2013).
lung carcinoma (5 papers, 2020 to 2025). "Four single-nucleotide polymorphisms of the CYP4F2 and CYP3A5 genes were genotyped, and their correlations with the risk of lung cancer were examined using Chi-square test and logistic regression analysis." (PMID 32350633, 2020). "Our research confirms that CYP4F2 and CYP3A5 gene polymorphisms are associated with the risk of lung cancer." (PMID 32350633, 2020). "Another study confirmed that CYP3A5 was associated with lung cancer in the population of Taiwan, China." (PMID 32350633, 2020). "However, little research has been done about the association between CYP4F2 and CYP3A5 gene polymorphisms and lung cancer in the Chinese Han population of mainland China." (PMID 32350633, 2020). "This study aimed to explore whether the polymorphisms of CYP4F2 and CYP3A5 are correlated with the risk of lung cancer development." (PMID 32350633, 2020). "CYP4F2 and CYP3A5 gene polymorphisms are associated with the reduced risk of non-small cell lung cancer, and its correlation is related to patients’ age and sex and pathological type of lung cancer." (PMID 32350633, 2020). "This suggests that CYP3A5 gene may be related not only to the risk and prognosis of lung cancer, but also to the treatment and drug selection of lung cancer." (PMID 32350633, 2020). "It was found that the expression of CYP3A5 gene in cancer tissues is lower than that in para-tumor tissues, and there was a worse prognosis in lung cancer patients with lower expression." (PMID 32350633, 2020). "We believe that our results will encourage more people using larger sample sizes to further confirm the relationship between CYP4F2 and CYP3A5 genes and lung cancer, as well as their specific mechanisms in the occurrence and development of lung cancer in the future studies." (PMID 32350633, 2020). "In addition, we found that CYP3A5 gene was low expressed in lung squamous cell carcinomas, and the survival rate was lower among the lung cancer patients with low expression." (PMID 32350633, 2020). "Similarly, in a study of Taiwanese of China, CYP3A5 has been confirmed to play a protective role in the development of lung cancer." (PMID 32350633, 2020). "Therefore, in this study, four SNP locus in CYP4F2 and CYP3A5 genes were analyzed to explore the association between the polymorphisms of CYP4F2 and CYP3A5 genes and the risk for lung cancer." (PMID 32350633, 2020). "Moreover, lung cancer metastasis is inhibited by CYP3A5 through regulation of the ATOH8/Smad1 axis." (PMID 39754188, 2025). "Meanwhile, we generated KM plots based on prognostic data from Kaplan-Meier Plotter and only CYP3A5 and MAOB showed consistent pattern of gene expression and prognosis, which genes with lower expression in lung cancer were correlated with a better prognosis." (PMID 38434969, 2024). "Our meta-analysis revealed the lack of association of CYP2R1 (rs10741657), CYP27B1 (rs3782130), CYP27B1 (rs10877012), CYP24A1 (rs6068816), CYP24A1 (rs4809960), CYP3A5 (rs776746), GC (rs7041), GC (rs4588), and VDR (ApaI: rs7975232) with lung cancer." (PMID 38482381, 2024).
neutropenia (5 papers, 2018 to 2022). A decrease in the number of neutrophils found in the blood. "Clozapine pharmacokinetics is influenced by CYP3A4 and CYP3A5 activity, as well as polymorphisms in HLA-B that can cause clozapine-induced neutropenia." (PMID 35722694, 2022). "The SNP CYP3A5*3 6986G allele was revealed to predict neutropenia in patients with breast cancer receiving docetaxel and was associated with taxane-induced neuropathy in other studies." (PMID 29861877, 2018).